IL33 (interleukin 33)
Diseases named in the same sentence as IL33 in open-access papers (continued):
Sharing a sentence is not in itself a finding about the gene and the disease.
infection (continued). "In the present study, we confirmed that IL-33 also had a deleterious effect on infection control in the spleen, as both IL-33 and ST2 receptor deficiency resulted in better control of parasite burdens in the spleen of mice infected with L. donovani, irrespective of the genotype background." (PMID 32571430, 2020). "However, it was shown that infection with the intestinal worm Nippostongylus brasiliensis triggers epithelial cells to release IL-25 and IL-33, which in turn cause ILC2 expansion in mice." (PMID 32140157, 2020). "Additionally, compared with WT mice, unvaccinated Il33−/− mice showed the same susceptibility to infection." (PMID 32210964, 2020). "Indeed, flow cytometry revealed that IL-33 treatment caused a dramatic switch in the myeloid cells of the colon by day 2 post infection, decreasing pro-inflammatory neutrophil and monocyte frequencies and numbers." (PMID 31221971, 2019). "To determine if the reduction of ILC2s in Il33−/− mice was restored by other mechanisms to the level of WT mice after the first 2 weeks post-infection, we infected WT and IL-33-deficient mice with S. venezuelensis and analyzed the cell population in the BALF over the following 4 weeks." (PMID 30283458, 2018). "ST2/IL-33 signaling has been implicated in protection from various infections, which could impact the gut." (PMID 28484466, 2017). "We have proposed a pathogenic role of IL-33 in endothelial dysregulation during the infection." (PMID 26943125, 2016). "IL-33-/- and WT mice both lost body weight from 4 to 8 dpi; however, IL-33-/- mice had significantly less weight loss than did WT mice and were considerably more active throughout the course of infection as compared to WT mice." (PMID 26943125, 2016). "To determine whether reduced IL33 expression during chronic H pylori–SS1 infection was caused by loss of SMCs we performed IL33 and UEA1 immunofluorescence on the stomach of 7-day and 2-month H pylori–SS1–infected mice." (PMID 28210674, 2015). "The apparent association of IL-33 expression with contractile forces in both smooth muscle cells and myofibroblasts, supports an important role of IL-33 in the response to tissue injury, in addition to its roles in the response to infection." (PMID 18836528, 2008). "The interleukin-1 (IL-1) cytokine family, including IL-1α, IL-1β, IL-18, IL-33, IL-36α, IL-36β, and IL-36γ, acts as DAMPs and stimulates sterile inflammation due to tissue necrosis, while also enhancing inflammation associated with tissue damage from infection." (PMID 41214565, 2025). "Our results indicate that IL-33 may protect gastric tissue from loss of homeostasis caused by deleterious effects of H. pylori components and the inflammatory response developed during infection." (PMID 32151084, 2020). "Interestingly, when infection becomes chronic, hepatic iNKT lymphocytes are progressively reduced in number, conceivably resulting in a loss of sensitivity of iNKT lymphocytes to IL-18 and/or IL-33." (PMID 31507607, 2019). "Western blot analyses indicated infection-associated GFAP upregulation and IL-33 alterations across brain regions, whereas co-therapy shifted these markers toward uninfected levels in a region- and strain-specific manner." (PMID 41652430, 2026). "Toxin B–specific antibodies (IgG, IgM, and IgA) 15 days after infection were higher in cecal contents and plasma of IL-33–treated mice." (PMID 40048372, 2025). "By supplementing with recombinant IL-33, we evaluated the impact of trTregs and other IL-33-responsive immune subsets on tissue damage, parasite control, and infection progression." (PMID 39883714, 2025). "Administering interleukin-33 at early infection times not only boosted trTregs but also expanded other reparative and antiparasitic immune cells." (PMID 39883714, 2025). "We observed that depletion of ILC2s abrogated IL-33–induced toxin B specific antibody production estimated in plasma and cecal content antibodies collected at 15 days after infection." (PMID 40048372, 2025).
infection (continued). "A similar IL-33 induction of antitoxin B antibody (IgG) was seen after infection with the classical C. difficile strain VPI 10463." (PMID 40048372, 2025). "Forty days after a primary infection with C. difficile strain R20291 with IL-33 treatment, mice were reinfected with either R20291 or VPI 10463." (PMID 40048372, 2025). "Upon exposure to external insults such as injury and infection, the epithelium releases alarmins including interleukin-25 (IL-25), IL-33, and thymic stromal lymphopoietin (TSLP), which assist in initiating and amplifying the immune response." (PMID 41246133, 2025). "At this earlier stage of infection, we found a distinct response, evidencing particular kinetics for IL-33’s effects." (PMID 39883714, 2025). "Prior to infection with the hypervirulent epidemic R20291 strain, mice were given antibiotics, and IL-33 protein was administered daily for 5 days by intraperitoneal injection (0.75 μg/mouse)." (PMID 40048372, 2025). "We found an increase in the gene expression of epithelial-derived IL-25 and IL-33 on day 3 after infection in adult cells." (PMID 40143308, 2025). "In contrast, A. fumigatus-infected eyes exhibited increased disease severity, i.e., corneal haze, opacity, and hypopyon in IL-33 KO mice both at 24 and 48 h post-infection." (PMID 40512033, 2025). "Other pro-inflammatory factors like IRF5, IL-12B, IL-1RN, IL-22, IL-8, and IL-33 significantly increased at 48 hpi in weaned piglets compared to newborn piglets after infection." (PMID 40589734, 2025). "In line with the trTregs and ILC2 responses, early infection in IL-33-treated mice progressed with a tendency toward reduced GOT and CPK levels, with no changes in LDH and GPT activity, or glucose concentrations." (PMID 39883714, 2025). "In the case of MHV-JHM infection, changes in expression (from 0% to 100%) were visible in IL-6, IL-18, IL-33, ENA-78 (CXCL5), GRO alpha (CXCL1), IP-10 (CXCL10), MCP-1 (CCL2), MIP-1 beta (CCL4), MIP-2 alpha (CXCL2), RANTES (CCL5), and TNF alpha." (PMID 40358160, 2025). "Overexpressed in keratinocytes of AD patients, IL-33 is rapidly released in response to injury or infection, triggering Th2 polarization by activating immune cells such as mast cells and group 2 innate lymphoid cells (ILC2s) to produce IL-4, IL-5, and IL-13." (PMID 41020006, 2025). "Primary infection in mice varied the most on principal component 1 (PC1), driven by metrics such as body weight loss, AM number, and IL-33 concentration." (PMID 41190814, 2025). "To explore the effects of IL-33 while avoiding the restrictive environment present at the peak of T. cruzi infection, we implemented early treatment during the first week of infection." (PMID 39883714, 2025). "Similar to i.n. papain and IL-33+IL-25 activation of ILC2s, Blimp-1 was expressed in lung ILC2s five days after infection." (PMID 40297693, 2025). "Chronic exposure to stimuli such as PFOS, smoking, air pollution, or pathogen infection induces IL-33 secretion by airway epithelial cells." (PMID 40995116, 2025). "In line with the previous findings, our gene profiling on DCs upon NK depletion under Cm infection also indicates the upregulated genes related to type II cytokines and signaling such as Il33, Il9b, and Il18bp." (PMID 40332391, 2025). "There was a significant influx of CD11c+ dendritic cells in MLN of the IL-33–treated group prior to the infection; however, only a small number of these dendritic cells expressed activation markers such as CD86." (PMID 40048372, 2025). "Altogether, these findings demonstrate that early IL-33 administration can improve the course of acute infection by reducing tissue damage and enhancing parasite control." (PMID 39883714, 2025). "IL-33, an epithelial and endothelial cell damage alarmin, was induced by the infection at 3 dpi but returned to baseline by 7 dpi." (PMID 40854598, 2025).
infection (continued). "Evaluations at different time points post-infection revealed that IL-33’s effects on various immune cell subsets followed distinct kinetics." (PMID 39883714, 2025). "The expression of IL-1β, IFN-α2, IFN-γ, TNF-α, MCP-1 (CCL2), IL-6, IL-8 (CXCL8), IL-10, IL-12p70, IL-17A, IL-18, IL-23, and IL-33 was assessed in apical washes at different time points after infection using a 13-plex immunoassay." (PMID 40143308, 2025). "While most cytokines are actively synthesized within cells, IL-33 is produced passively in response to tissue damage or cell necrosis, indicating its role as a signaling molecule following cellular infection, stress, or trauma." (PMID 39925809, 2025). "Concentrations of the alarmin IL-33 were depressed in the primary infection mice most prevalently at days 3–10 post-challenge, ultimately recovering to the levels of all other treatment groups by 28 DPC." (PMID 41190814, 2025). "In the early stage of infection, IL-33 activates ILC2s, which, in turn, prevent Th1/Th17-mediated inflammation." (PMID 38785567, 2024). "We also discovered that infection with S. aureus intensifies skin inflammation by enhancing IL-33 release from keratinocytes, and this is dependent on both TLR2 signaling and the necroptotic pathway." (PMID 38319737, 2024). "Administration of inhibitors of NFATc1 and HIF-1α in infected mice depicted similar observations and justifies the role of these two transcription factors in IL-33 secretion and propagation of infection." (PMID 38750790, 2024). "These cells expand robustly after infection with intestinal parasites such as N. brasiliensis or in response to exogenous IL-33 or IL-25, and they are the major innate IL-13 resources under these conditions." (PMID 39559705, 2024). "The researchers concluded that IL-33 holds potential for cancer therapy, either through direct injection or by fostering the production of potent infection-fighting (immune)?" (PMID 38825642, 2024). "The research found that IL-33 can both help and hinder cancer growth, contingent upon its concentration and the specific infection-fighting (immune)?" (PMID 38825642, 2024). "Mesothelial IL-33, upon infection, signals the induction of a peritoneal immune response, while stromal IL-33 facilitates a regulatory cycle." (PMID 38163110, 2024). "Eosinophils, which play a vital role in the host defense against parasites and infections, are activated by IL-33 for allergic reactions and tissue repair." (PMID 40236667, 2024). "When inflammation, injury or infection occurs, IL-33 functions as an alarmin to immune system and its expression is up-regulated and promptly released to the outside of the cell." (PMID 39267790, 2024). "Since a recent report has mentioned the involvement of cAMP in IL-33 production, we focused our search on IL-33 signaling starting from the elevated levels of intracellular cAMP in infection." (PMID 38750790, 2024). "The anti-inflammatory function of IL-33 in infection is primarily centered on reducing proinflammatory cytokines." (PMID 38750790, 2024). "Collectively, these results suggest that downstream of PLC, calcium-dependent activation of calcineurin is responsible for infection-mediated induction of IL-33 in macrophages." (PMID 38750790, 2024). "The study, done on mice, showed that lower concentrations of IL-33 facilitate cancer grow by increasing certain infection-fighting (immune)?" (PMID 38825642, 2024). "Interleukin-33 (IL-33), a protein that helps the body in combating infections, plays a double role in cancer growth, says a study by Kang and Bae." (PMID 38825642, 2024). "In response to tissue/cell damage, infection, necrosis, or oxidative stress, IL-33 is released by damaged or necrotic cells, which functions to regulate physiological and pathological processes related to chronic inflammation." (PMID 39713054, 2024). "All these observations strongly suggest that infection-induced EPAC activates the PLC/calcium/calmodulin axis leading to IL-33 production." (PMID 38750790, 2024).
infection (continued). "In our study, larva recovery from the infected brains was significantly reduced in IL-33-injected mice in the second and third weeks post-infection." (PMID 38787044, 2024). "Mast cells are a potent source of IL-33 during infection with intestinal nematodes such as H. polygyrus." (PMID 39559705, 2024). "Infection-mediated upregulation of IL-33 was markedly inhibited when INCA-6 and GN 44028 were administrated individually (43.5% and 35.4% inhibition, respectively)." (PMID 38750790, 2024). "In severe infection, sST2 acts as a negative regulator and combines with IL-33, thus participating in immunosuppression." (PMID 39640977, 2024). "In the infected groups in the 3rd week post-infection, the proportion of IgG1 increased when the mice were treated (from 41% to 50% when treated with IL-33 and to 56% and 57% when treated with anti-IL-33 and anti-ST2 mAb, respectively)." (PMID 38787044, 2024). "In response to harmful events such as infection, injury, or inflammation, barrier tissue cells, including epithelial cells, release IL-33." (PMID 40236667, 2024). "When cells were treated with DDA (100 μM for 1 h) followed by infection for 48 h, the level of IL-33 was decreased as compared to infected control (61.2%, p = 0.000330, F = 40.42)." (PMID 38750790, 2024). "Now, to delineate the precise mechanism of calcium-calmodulin–regulated IL-33 production in infection, an inhibitor-based approach was taken." (PMID 38750790, 2024). "Th2 cells and Tregs accumulate in the lung following H. polygyrus infection, and Th2 cells acquire innate-like properties, responding to secondary infection in an antigen-independent and IL-33-dependent manner." (PMID 38277692, 2024). "Conversely, higher concentrations of IL-33 counteract these effects, triggering anti-cancer responses by activating other infection-fighting (immune)?" (PMID 38825642, 2024). "Conversely, in the late stage of infection, IL-33 decreases, leading to M2 macrophage polarization, with the increase in STAT3 activation and promotion of tumor growth." (PMID 38785567, 2024). "By mimicking the natural route of S. aureus infection in patients with AD, our dry-skin mouse model further revealed that the exacerbated IL-33 release from an epicutaneous-infection with S. aureus was dependent on TLR2 signaling and necroptosis." (PMID 38319737, 2024). "In cases of severe infections, sST2 functions as a negative regulator by binding to IL-33, thereby contributing to immunosuppression." (PMID 39640977, 2024). "Compared to the non-infected mice, when the infected mice were injected with IL-33, the levels of IgG increased extremely significantly in the 3rd and 4th week post-infection (p < 0.001) and reached a peak in the 4th week post-infection." (PMID 38787044, 2024). "During infection, basophils are activated by IL-3, IL-33, TSLP, FcεRIα cross-linking, and Notch signaling to produce IL-4, bioactive lipids, amines, and proteases." (PMID 38277692, 2024). "While we did not detect vaccination-associated differences in plasma levels for IL-5, IL-23, IL-33, and CCL2/MCP-1, we observed a step-wise reduction of IL-18 levels after post-infection vaccinations in individuals with ongoing PCC." (PMID 38316833, 2024). "Next, we tried to detect the transcription factors responsible for IL-33 induction during infection." (PMID 38750790, 2024). "In experimental cerebral toxoplasmosis, IL-33 is expressed by oligodendrocytes and astrocytes during infection and is required for control of parasite burden." (PMID 39559705, 2024). "To test this, we titered virus from the cortex, hippocampus, cerebellum, brainstem, and peripheral organs of Il1rl1–/–, Il33–/–, and B6/J infected mice at 7 days post-infection (DPI), a timepoint corresponding to peak disease." (PMID 37983247, 2023). "IL-33 is a cytokine of the IL-1 family potentiated with pro-inflammatory and anti-inflammatory effects in response to infection." (PMID 36875710, 2023).
infection (continued). "TNF-α, IL-10, IL-13, and IL-33 were significantly (p < 0.05) increased in severe infection comparison to a mild infection in children with HRSV coinfection with HBoV." (PMID 37239461, 2023). "Under conditions of stress or infection, the full-length IL-33 can be released from the cells, functioning as an alarmin or danger signal, enhancing inflammation when released from necrotic cells." (PMID 37762328, 2023). "Studies have also examined the whole-tissue transcriptional responses to vegetative C. difficile in a murine infection model, where IL-33 was shown to be upregulated during infection." (PMID 37615437, 2023). "Interleukin (IL)-33 is a broad-acting alarmin cytokine that can drive inflammatory responses following tissue damage or infection and is a promising target for treatment of inflammatory disease." (PMID 37330528, 2023). "Our data shows that, as compared to ancestral Wuhan-Hu-1 strain, BA.5 infection in hACE2.Tg mice shows an overall decrease in the mRNA expression of IL-4, IL-6, IL-17A, and IL-33." (PMID 37704701, 2023). "Infection and autoimmune diseases often prompt IL-33’s release, further illustrating the critical role of this cytokine in immune responses." (PMID 37762328, 2023). "Taken together, these data indicate that IL-33 treatment is detrimental to the outcome of infection with F. tularensis LVS." (PMID 36602520, 2023). "Whereas, IL-10, IL-13, and IL-33 were significantly (p < 0.05) increased in severe infection compared to a mild infection in children with HBoV." (PMID 37239461, 2023). "The nature of the antiviral immune response orchestrated by IL-33 depends on the site of infection, the duration and the cytokine environment." (PMID 38035159, 2023). "A study has confirmed that the balance between IL-33 and IL-1 signaling regulates the immune response during infection." (PMID 37153553, 2023). "We found that the S. aureus clinical isolate triggered the release of IL-33 in an infection dose- and time-dependent manner." (PMID 37261337, 2023). "This expansion was also observed in the infected lung, albeit to a lesser extent than in IL-33–treated uninfected mice, suggesting that infection antagonized the ILC2 response even following IL-33–induced expansion." (PMID 36602520, 2023). "ILC2 proliferates rapidly in response to IL-33 activation and produces cytokines such as IL-13, IL-5, and IL-9, playing a crucial role as a major source of type 2 cytokines during early infection." (PMID 37686309, 2023). "Whereas, IL-10, IL-13, and IL-33 were significantly increased in severe infection compared to mild infection in children with HBoV." (PMID 37239461, 2023). "IL-33 protein is released from injured epithelial cells upon infections and inflammation as IL-33 stored in the nucleus of destroyed epithelial cells is set free." (PMID 37798647, 2023). "Using flow cytometry, we found that the infection-driven IL-33 produced by EpCAM+CD45− cells was significantly reduced in Il17a-KO mice compared to WT controls." (PMID 37783278, 2023). "They observed significantly higher IL33 expression at 72 h post-infection, demonstrating that infection induces the expression of IL-33 in the airway epithelium." (PMID 37631998, 2023). "TNF-α, IL-6, IL-8, IL-10, IL-13, and IL-33 in children with HRSV were significantly increased in severe infection compared to mild infection (p < 0.05) in children with HRSV." (PMID 37239461, 2023). "Upon an infection or tissue damage in the kidney, IL-33 acts as a nuclear sentinel to sense the injury and then warns the neighboring cells and tissues." (PMID 36859530, 2023). "Whereas, IL-10, IL-13, and IL-33 were significantly increased in severe infection in compared a mild infection in children with HBoV." (PMID 37239461, 2023).